HSPB6 (heat shock protein family B (small) member 6)
Diseases named in the same sentence as HSPB6 in open-access papers (continued):
Sharing a sentence is not in itself a finding about the gene and the disease.
HSPB6 also shares sentences with these, for which no sentence is quoted: infection (15 papers); cardiac hypertrophy (12); cardiac ischemia (6); ischemia (5); heart disease (4); virus infection (4); Hyperglycemia (3); myocardial infarct (3); Ad. (2); Alzheimer's disease (2); cyst (2); diabetic cardiomyopathy (2); dilated cardiomyopathy (2); keloid (2); malaria (2); type 2 diabetes (2); acute lung injury (1); Allergy (1); Anaplasma phagocytophilum infection (1); arbovirus infection (1); Arrhythmia (1); asthma (1); Cardiovascular Disease (1); cataract (1); Cerebral ischemia (1); cervical squamous cell carcinoma (1); chronic obstructive pulmonary disease (1); cognitive decline (1); Colon Cancer (1); congestive heart failure (1).
A further 24 diseases each share a sentence with HSPB6 in 1 paper.